ANXA7 (annexin A7)
Diseases named in the same sentence as ANXA7 in open-access papers (continued):
Sharing a sentence is not in itself a finding about the gene and the disease.
epilepsy (1 paper, 2005). A brain disorder characterized by episodes of abnormally increased neuronal discharge resulting in transient episodes of sensory or motor neurological dysfunction, or psychic dysfunction. "We have previously reported the expression of Annexin A7 in human temporal neocortex and hippocampus obtained from neurosurgery for therapy-refractory epilepsy and found the two Annexin A7 isoforms restricted to the cytoplasm and nuclei of astrocytes, whereas neurons lacked any signal." (PMID 15819996, 2005).
injury (1 paper, 2022). Damage inflicted on the body as the direct or indirect result of an external force, with or without disruption of structural continuity. "However, it remains unclear whether circulating ANXA7 levels are associated with hemorrhagic severity and clinical outcome after acute brain injury." (PMID 36003296, 2022). "However, to the best of our knowledge, ANXA7 has not been measured in human peripheral blood after acute brain injury." (PMID 36003296, 2022).
intracerebral hemorrhage (1 paper, 2022). A cerebrovascular disorder characterized by bleeding into one or both cerebral hemispheres including the basal ganglia and the cerebral cortex. "This study aimed to assess the clinical utility of serum ANXA7 as a predictor of severity, early neurological deterioration (END), and prognosis after intracerebral hemorrhage (ICH)." (PMID 36003296, 2022).
ischemic stroke (1 paper, 2025). A stroke disorder caused by obstruction of blood flow to the brain, due to thrombotic (local blood clot formation) or embolic (due to a blood clot or other material traveling from another site) event. "This investigation demonstrated that several neuron-expressed annexins, including annexin (Anx) A2, AnxA5, AnxA6, and AnxA7, play a role in the development of acute neuronal CaP formation and deposition in the mouse model of ischemic stroke." (PMID 39820937, 2025). "This investigation demonstrated that the neuron-expressed, plasma membrane-associated Ca2+-binding proteins annexin (Anx) A2, AnxA5, AnxA6, and AnxA7 contributed to neuronal CaP deposition in the mouse model of ischemic stroke." (PMID 39820937, 2025). "Ischemic stroke did not cause a substantial change in the relative expression of AnxA2, AnxA5, AnxA6, and AnxA7 in the cortical neurons in reference to sham controls." (PMID 39820937, 2025).
lung carcinoma (1 paper, 2024). "The interaction between GRP78 and annexin A7 (ANXA7) was facilitated after the use of ZBM-H, which was accompanied by an increased phosphorylation of ITGB4, which in turn regulated lung cancer cell behavior." (PMID 39169946, 2024).
malaria (1 paper, 2021). Malaria is a serious and sometimes fatal disease caused by a parasite that commonly infects a certain type of mosquito which feeds on humans. "Eryptosis was also accelerated in Plasmodium-infected Anxa7−/− erythrocytes, indicating that AnxA7 downregulation may partially protect against malaria in vivo." (PMID 33810523, 2021).
metastasis (1 paper, 2014). The spread or migration of cancer cells from one part of the body (where they first appeared) to another. "On the other hand Annexin A7 correlates with tumor malignancy and lymph node metastasis." (PMID 24392146, 2014).
multiple myeloma (1 paper, 2020). "This study aimed to investigate whether annexin A7 (ANXA7) could promote the cell cycle, proliferation and cell adhesion-mediated drug resistance (CAM-DR) of multiple myeloma (MM) cells by up-regulating cell division cycle 5-like (CDC5L)." (PMID 32526706, 2020).
osteosarcoma (1 paper, 2023). A usually aggressive malignant bone-forming mesenchymal neoplasm, predominantly affecting adolescents and young adults. "In a proteomic screen, AnxA7 and Anx11 have been detected in mRNP complexes from human embryonic kidney cells, and AnxA11 is a component of mRNP complexes from U2OS bone osteosarcoma cells." (PMID 37397259, 2023).
ovarian carcinoma (1 paper, 2019). A malignant neoplasm originating from the surface ovarian epithelium. "Both databases showed that ANXA2, ANXA3, ANXA8, and ANXA11 mRNA expression levels were upregulated in ovarian cancer compared with normal tissues, while ANXA5,ANXA6, and ANXA7 mRNA expression levels were downregulated." (PMID 31474227, 2019). "In addition, the expression levels of ANXA1, ANXA4, ANXA5, ANXA6, ANXA7 and ANXA13 were lower in ovarian cancer than in the normal controls." (PMID 31474227, 2019).
ovarian serous tumor (1 paper, 2019). A benign, borderline, or malignant epithelial tumor of the ovary characterized by the presence of neoplastic epithelial cells that, in well differentiated tumors, resemble the epithelial cells of the fallopian tube and, in poorly differentiated tumors, show anaplastic features. "ANXA7 mRNA downregulation was significantly correlated with poor PFS in patients with ovarian serous tumors, and ANXA9 mRNA upregulation was significantly correlated with poor OS and PFS in patients with ovarian serous tumors." (PMID 31474227, 2019).
thyroid cancer (1 paper, 2024). "In this study, we investigated the relationship between BRAF V600E mutation, ANXA7 expression, and their roles in thyroid cancer progression and chemoresistance." (PMID 39684934, 2024). "In this study, we explored the molecular mechanisms underlying the reduction in ANXA7 expression in thyroid cancer and its association with drug resistance pathways." (PMID 39684934, 2024). "This study investigates the tumor-suppressive role of Annexin A7 (ANXA7) in thyroid cancer, focusing on its potential impact on tumor behavior and therapeutic response." (PMID 39684934, 2024). "The inverse relationship between higher levels of BRAF V600E and ANXA7 can be seen when comparing these cell lines, indicating a tumor suppressive role in thyroid cancer that is inhibited with the aggressive and oncogenic BRAF V600E mutation." (PMID 39684934, 2024). "Our previous tissue microarray studies demonstrated that ANXA7 expression is notably lower in thyroid cancer tissues compared to other cancer types, suggesting a potential tumor suppressive function of ANXA7 in the thyroid." (PMID 39684934, 2024). "Future efforts will focus on high-throughput screening approaches to explore ANXA7-targeted therapeutic strategies for thyroid cancer." (PMID 39684934, 2024). "Our analysis, which included RNA sequencing and protein profiling, revealed reduced ANXA7 expression in thyroid cancer cells, particularly in those harboring the BRAF V600E mutation." (PMID 39684934, 2024). "When the mRNA expression levels were viewed, both BRAF and ANXA7 had mid-range levels in thyroid cancer cases (Cancer Cell Line Encyclopedia, CCLE)." (PMID 39684934, 2024). "Our findings suggest that the decreased expression of ANXA7 may contribute to the development and progression of thyroid cancer by impairing cellular mechanisms that normally inhibit tumor growth and metastasis." (PMID 39684934, 2024). "By investigating the interplay between ANXA7 expression and BRAF mutation (V600E), our study offers promising insights into overcoming resistance to the BRAF V600E mutation or MAPK-targeting drugs in the treatment of thyroid cancer." (PMID 39684934, 2024). "However, when looking at the protein expression levels of these genes through reverse-phase protein array (RPPA), ANXA7 expression was lowest in thyroid cancer (MD Anderson Cell Line Project)." (PMID 39684934, 2024). "This reduction in ANXA7 may influence the survival of thyroid cancer cells, particularly under therapeutic stress, where drug resistance is a significant challenge." (PMID 39684934, 2024). "It is also hypothesized that the downregulation of ANXA7 expression could serve as an early and stage-specific biomarker for thyroid cancer or other thyroid-related malignancies." (PMID 39684934, 2024). "Therefore, the decrease in ANXA7 expression may play a critical role in the development and progression of thyroid cancer." (PMID 39684934, 2024). "The role of Annexin A7 (ANXA7) in thyroid cancer presents a complex but intriguing area of investigation, given its high expression levels in the normal thyroid gland and significant downregulation in thyroid cancer tissues." (PMID 39684934, 2024).
thyroid- (1 paper, 2024).
tumor (38 papers, 2008 to 2025). "The results demonstrated a robust enrichment of ZEB1 and HDAC1 on the promoters of CLDN7 and ANXA7, all of which are implicated in tumor suppression." (PMID 39193340, 2024). "The tumor suppressor function of the calcium/phospholipid-binding Annexin-A7 (ANXA7) has been shown in ANXA7-deficient mice and validated in human cancers." (PMID 39684934, 2024). "Functionally, ANXA7 has been implicated in membrane trafficking, exocytosis, calcium homeostasis, and tumor suppression." (PMID 37240163, 2023). "Membrane-linked protein A7 (ANXA7) is associated with tumours, which are known to be lymphatic metastasis-related proteins." (PMID 33397392, 2021). "ANXA7 is associated with the cell membrane transport, signal transduction, proliferation and invasion of tumour cells." (PMID 33397392, 2021). "Tumor suppressor function of the calcium/phospholipid-binding Annexin-A7 (ANXA7) has been shown in Anxa7-deficient mice and validated in human cancers." (PMID 24864229, 2014). "Further mechanistic studies will provide more insight into Annexin A7 tumor suppressor function for potential diagnostic and therapeutic uses." (PMID 24188284, 2013). "However, the exact mechanism which causes the tumor sensitization by ANXA7 expression remains to be clarified." (PMID 39684934, 2024). "Moreover, decreased ANXA7 mRNA levels were significantly associated with lower OS, which conformed to its role as a tumour suppressor." (PMID 39290334, 2022). "This was accompanied by reduced expression of several tumour suppressors, DNA repair- and apoptosis-related genes, indicating the development of genomic instability driving disease progression upon partial loss of AnxA7." (PMID 33810523, 2021). "In addition, potential roles of AR-A014418 in downregulation of splicing factors were reflected with decrease in Anxa7 (VA) variant and increase in Anxa7 WT tumor suppressor transcript and protein." (PMID 24550987, 2014). "In recent years, considerable amounts of data have accumulated describing the inactivation of ANXA7-GTPase in a variety of human malignancies and demonstrating the tumor suppressor potential of ANXA7-GTPase." (PMID 39684934, 2024). "Our results show that ANXA7, a known tumor suppressor gene that has been extensively studied by our laboratory for the past decade, is correlated to favorable outcomes." (PMID 39684934, 2024). "This combination increased ANXA7 expression and enhanced apoptotic signaling, suggesting a tumor-suppressive ANXA7-BRAF-p21 axis." (PMID 39684934, 2024). "We, therefore, measured the mRNA levels of ANXA7 and IP3 receptor in tumor cells treated with the adenovirus vector alone, as well as with wt-ANXA7 and DN-ANXA7J." (PMID 37240163, 2023). "The modulation of ANXA7 structural flexibility, including N-terminal positioning, is a promising approach for further evaluation of ANXA7 in PS-associated PCD and tumor suppression." (PMID 37240163, 2023). "ANXA7′s tumor suppressor function was discovered serendipitously, when ANXA7 knockout mice were found to be laden with tumors)." (PMID 37240163, 2023). "The murine model thus indicated that tumor suppression by ANXA7, which is involved in the Ca-regulated phospholipid turnover, can be particularly associated with the PI3K pathway." (PMID 37240163, 2023).
tumor (continued). "Here, we identified a dominant-negative triple mutant (DNTM/DN-ANXA7J) that dramatically suppressed the ability of ANXA7 to fuse with artificial membranes while also inhibiting tumor cell proliferation and sensitizing cells to cell death." (PMID 37240163, 2023). "ANXA7 has also been reported to play a role in cancer, either oncogenic or oncosuppressor depending on the tumor subtypes." (PMID 36247003, 2022). "ANXA7 GTPase is considered a tumour suppressor frequently inactivated by genomic alterations at 10q21 in a variety of human malignancies, including KIRC." (PMID 39290334, 2022). "Silencing AnxA7 in a xenograft model for gastric cancer induced apoptosis, altered the expression of apoptosis-mediating genes, and inhibited tumour growth." (PMID 33810523, 2021). "According to circRNA microarray analysis based on 40 pairs of LUAD tissues and non-tumor tissues, a novel circ-ANXA7 was up-regulated in LUAD, which was verified in LUAD tissues and cells by RT-qPCR." (PMID 33536022, 2021). "In human cancers, deletions at the Anxa7 gene locus on chromosome 10q21 are common, and a substantial number of studies identified AnxA7 and its GTPase activity as a tumour suppressor with roles in cell death, motility and invasion in a variety of cancers." (PMID 33810523, 2021). "In these studies, SEC-induced AnxA7 bound and promoted the nuclear translocation of integrin β4, which inhibited the growth of A549 xenograft tumours in the avian embryo model." (PMID 33810523, 2021). "Based on our microarray analysis results, circ-ANXA7 was found to be prominently up-regulated in LUAD tissues (n = 40) compared to non-tumor tissues (n = 40)." (PMID 33536022, 2021). "On the other hand, AnxA7 upregulation and tumour-promoting roles in the initiation and progression of liver, colorectal, gastric, nasopharyngeal and breast cancer, have been reported." (PMID 33810523, 2021). "The protein Annexin A7 (ANXA7) having functional role in tumor suppression was found in high abundance, almost 2-fold upregulated in GS treated cells." (PMID 31581454, 2019). "The results of this TMA study identified ANXA7 as a new prognostic factor and indicates a bimodal correlation to tumor progression." (PMID 30321230, 2018). "The ANXA7 is a tumor suppressor and a member of the calcium-dependent phospholipid binding proteins." (PMID 30321230, 2018). "The tumor suppressor gene (TSG) function of the Ca/phospholipid-binding Annexin-A7 (ANXA7, NP001147.1, NCBI) has been demonstrated in our previous studies, including Anxa7(+/−) murine model and ANXA7 tissue microarray profiling in normal versus tumor tissues." (PMID 24864229, 2014). "Annexin A7 can also modulate neoangiogenesis and tumor invasiveness through its involvement in VEGFR1 signaling." (PMID 24188284, 2013). "Next, we analyzed the expression and subcellular localization of Annexin A7 in mouse primary tumor tissue and metastatic lymph nodes using immunohistochemistry." (PMID 24188284, 2013). "In this study, we found that Annexin A7 expression was different in metastasized lymph nodes and primeval tumor cells derived from Hca-P and Hca-F cells." (PMID 24188284, 2013). "The annexins with the exception of annexin A7 showed increased immunostaining in primary tumours in comparison to normal colon." (PMID 18071363, 2008). "Similarly, in Hca-F cells—a mouse HCC model with high lymphatic metastatic potential—miR-124-3p exerts tumor-suppressive effects by targeting ANXA7, thereby inhibiting tumor growth, invasion, and lymphatic metastasis." (PMID 40717977, 2025).